TFG (trafficking from ER to golgi regulator)
Description:
Plays a role in the normal dynamic function of the endoplasmic reticulum (ER) and its associated microtubules. Required for secretory cargo traffic from the endoplasmic reticulum to the Golgi apparatus.
Synonyms: TF6; FLJ36137; SPG57; HMSNP; TRKT3
Tractability: PROTAC: ubiquitination databases record sites on it; its protein half-life has been measured.
Gene: Protein-coding gene on chromosome 3 (100,709,295 to 100,748,965, forward strand). Ensembl gene ENSG00000114354.
Subcellular location: Endoplasmic reticulum
Subcellular location (Human Protein Atlas): Vesicles; Cytosol
Pathways (Reactome):
Disease: Signaling by ALK fusions and activated point mutants
Vesicle-mediated transport: COPII-mediated vesicle transport
Gene Ontology:
Molecular function: identical protein binding; protein binding
Biological process: endoplasmic reticulum to Golgi vesicle-mediated transport; positive regulation of canonical NF-kappaB signal transduction; COPII vesicle coating
Cellular component: endoplasmic reticulum; endoplasmic reticulum exit site; cytoplasm; cytosol
Genetic constraint (gnomAD): Loss-of-function variants: 17 observed, 43.14 expected, observed/expected ratio (o/e) 0.39, 90% interval 0.27 to 0.59. The upper end of that interval is the gene's LOEUF score, 0.59, which puts it in group 2 of 6, group 1 being the genes least tolerant of losing a copy. Missense variants: 365 observed, 440.53 expected, observed/expected ratio (o/e) 0.83, 90% interval 0.76 to 0.9. Synonymous variants: 161 observed, 150.98 expected, observed/expected ratio (o/e) 1.07, 90% interval 0.94 to 1.22.
Homologues: Orthologues: chimpanzee TFG (100% identical), macaque TFG (99% identical), guinea pig TFG (96% identical), dog TFG (95% identical), rabbit TFG (94% identical), mouse Tfg (94% identical), rat Tfg (90% identical), pig TFG (90% identical), tropical clawed frog tfg (80% identical), zebrafish tfg (68% identical), Caenorhabditis elegans tfg-1 (30% identical), Caenorhabditis elegans Y71A12B.10 (14% identical).
Diseases named in the same sentence as TFG in open-access papers:
TFG is named in the same sentence as 72 diseases in open-access papers, as found by Europe PMC text mining. Sharing a sentence is not in itself a finding about the gene and the disease. The quoted sentences say what the papers report.
papillary thyroid cancer (7 papers, 2014 to 2022). "TFG-MET (MET proto-oncogene receptor tyrosine-kinase) translocation was reported in a follicular variant of the papillary thyroid carcinoma." (PMID 31349573, 2019). "In at least two out of these four cases (KIF5B–MET in lung adenocarcinoma and TFG–MET in thyroid papillary carcinoma), the predicted chimeric protein follows the classic activation paradigm, fusing dimerization motifs to an intact kinase domain." (PMID 25204415, 2014). "In papillary thyroid cancers (PTCS), the new gene fusion involves exons 1–4 from the 5′ end of the TFG fused to the 3′ end of RET tyrosine kinase, leading to a TFG-RET fusion that transforms immortalized human thyroid cells in a kinase-dependent manner." (PMID 36337204, 2022). "In our opinion, the strong correlations of the (not yet assigned to a pathway) NEMP1 gene with the oncogenes TFG and HRAS indicate its potential role in the papillary thyroid cancer." (PMID 31349573, 2019). "In thyroid cancer the first description was the TFG-MET fusion, found in one papillary thyroid cancer after the depth analysis of the Cancer Genome Atlas (TCGA) RNA-seq data." (PMID 31040922, 2019). "In up to 12% of papillary thyroid cancer patients, the 3′ exons of NTRK1 with the kinase domain had been found to fuse with the 5′ exons of various thyroid-expressed genes (TPM3, TPR, TFG) in frame." (PMID 24647444, 2014).
thyroid cancer (7 papers, 2014 to 2025). "The discovery of TFG-MET fusion in this setting broadens the known molecular spectrum of radiation-associated thyroid carcinomas and raises important questions about the potential for underrecognized rare gene fusions to drive tumorigenesis following radiation exposure." (PMID 40636652, 2025). "TFG was initially identified as an oncogene causing thyroid cancer." (PMID 36337204, 2022). "ThyroSeq v3, a targeted next-generation sequencing (NGS) panel evaluating point mutations, gene fusions, and copy number alterations common to thyroid cancer, identified a TFG-MET gene fusion within the tumor sample." (PMID 40636652, 2025). "In thyroid cancer, the TRK-T3 oncogene is produced at the C-terminus of neurotrophic tyrosine kinase receptor 1 (NTRK1) fused with the NH2 terminus encoded by the TFG sequence." (PMID 36337204, 2022). "In particular, NTRK1 has been found to fuse with tropomyosin in colon cancer, TPM3, TPR, and TFG in thyroid cancer, and MPRIP and CD74 in lung cancer." (PMID 24647444, 2014). "Sequencing of this patient's tumor revealed a TFG-MET fusion, a rare genetic alteration that has been reported in only isolated cases of thyroid carcinoma." (PMID 40636652, 2025).
and sensory neuropathy (6 papers, 2015 to 2024). "Mutations in the Trk-fused gene (TFG) cause hereditary motor and sensory neuropathy with proximal dominant involvement, which reportedly has high co-incidences with diabetes and dyslipidemia, suggesting critical roles of the TFG in metabolism as well." (PMID 38681675, 2024). "Mutations in TFG are responsible for SPG57, an AR-HSP associated with optic atrophy and neuropathy but can also be responsible for AD motor and sensory neuropathy." (PMID 25758904, 2015). "Mutations within TFG have been associated with several distinct phenotypes, including HMSN‐P, hereditary spastic paraplegia (HSP), neuroaxonal dystrophy “plus” syndrome, (Catania, Battini, & Pippucci, 2018) and motor neuron disease with sensory neuropathy (Li, Meng, & Wu, 2019)." (PMID 32666699, 2020).
hereditary motor and sensory neuropathy (6 papers, 2017 to 2024). A group of slowly progressive inherited disorders affecting motor and sensory peripheral nerves. "Mutations in the TFG gene have been linked to various neurodegenerative diseases, including hereditary motor and sensory neuropathy (HMSN) and HSP." (PMID 38837630, 2024). "Biallelic mutations in TFG (tropomyosin receptor kinase) have been implicated in corticospinal axon pathology, causing neurological disorders, such as ALS, hereditary motor and sensory neuropathies (HMSNs), and Spastic paraplegia 57 (SPG57)." (PMID 38473862, 2024). "Additionally, inactivating TFG in mice is embryonic-lethal, and TFG point mutations have been identified in several patients with neurological diseases, including HSP, Charcot-Marie-Tooth disease, and hereditary motor and sensory neuropathy." (PMID 32053905, 2020). "The Trk-fused gene (TFG) is reportedly involved in the process of COPII-mediated vesicle transport and missense mutations in TFG cause several neurodegenerative diseases including hereditary motor and sensory neuropathy with proximal dominant involvement (HMSN-P)." (PMID 29026155, 2017).
hereditary spastic paraplegia (5 papers, 2017 to 2024). Hereditary spastic paraplegias (HSP) comprise a genetically and clinically heterogeneous group of neurodegenerative disorders characterized by progressive spasticity and hyperreflexia of the lower limbs. "These defects are also recapitulated in fibroblasts from a patient carrying an R106C TFG variant that has been previously associated with a complicated hereditary spastic paraplegia (HSP) phenotype." (PMID 34459017, 2021). "TFG mutations have previously been implicated in autosomal recessive hereditary spastic paraplegia (HSP), also known as SPG57." (PMID 38837630, 2024).
lung carcinoma (4 papers, 2010 to 2022). "On average, TFG mutations are found in 0.19% of all cancers; the most common types are breast cancer, colon cancer, and lung cancer." (PMID 36251702, 2022). "Multiple mutations in TFG have been shown in intestinal cancer, lung cancer, and stomach cancer." (PMID 36251702, 2022). "In lung cancer, the primary ALK fusion detected was identified as EML4-ALK, followed by TFG-ALK and KIF5-ALK, although other unknown fusions may also exist which can not be detected due to limits of present technology." (PMID 20624322, 2010). "In addition to TFG-ALK in lung cancer, some ALK fusions have been reported without histopathological evidence: TPM4-ALK in esophageal squamous cell carcinoma and EML4-ALK in colon and breast carcinomas." (PMID 22347464, 2012). "In lung cancer, 3 fusion partners of ALK have been reported—EML4, TFG, and KIF5B—although the presence of TFG-ALK in lung cancer has not yet been proven with histopathological evidence." (PMID 22347464, 2012).
prostate carcinoma (4 papers, 2014 to 2022). A carcinoma that arises from epithelial cells of the prostate gland. "Specific silencing of TFG expression in PC3 prostate cancer cells reduced cell amplification and caused premature cell failure." (PMID 36337204, 2022). "Nrf was also among the transcriptional factors associated with TFG expression in our previous microarray analysis using LNCaP cells (a prostate cancer cell line)." (PMID 29026155, 2017). "Regarding its role in cancer, TFG has been found to be preferentially up-regulated in prostate cancer cell lines and tissues, with TFG expression being associated with a higher probability of tumour recurrence following surgery." (PMID 24999993, 2014). "This is in line with a previous report which indicated that siRNA-mediated TFG knockdown inhibited cell growth in prostate cancer cell lines via induction of cellular senescence." (PMID 29026155, 2017). "Studies have shown that TFG protein is highly expressed in prostate cancer cells and tissues." (PMID 36337204, 2022).
breast carcinoma (3 papers, 2014 to 2022). "This study also adds to the molecular knowledge of breast cancer complexity by identifying 118 candidate fusion transcripts and many TaqMan supported fusion transcripts, all of which are novel except TFG->GPR128." (PMID 24727804, 2014).
Glucose intolerance (3 papers, 2017 to 2024). Glucose intolerance (GI) can be defined as dysglycemia that comprises both prediabetes and diabetes. "Whether patients with HSP, which is due to a homozygous mutation when TFG is the causative gene, have an associated glucose intolerance merits further study, but little is as yet known about this possible association." (PMID 29026155, 2017). "TFG deletion in the early phase of HFD feeding impaired adipose expansion in epiWAT, whereas TFG deletion after adipose tissue expansion triggered adipocyte death, both of which exacerbated hepatic steatosis and glucose intolerance." (PMID 38681675, 2024). "Collectively, TFG in pancreatic β-cells plays a vital role in maintaining both the mass and function of β-cells, and its dysfunction increases the tendency to develop glucose intolerance." (PMID 29026155, 2017).
hepatocellular carcinoma (3 papers, 2015 to 2021). A malignant tumor that arises from hepatocytes. "Pin1 has been implicated in colorectal cancer (β-catenin), breast cancer (Cyclin D, AP-1, Akt, centrosome duplication, Notch1), prostate cancer (TRK-fused gene [TFG]), glioblastoma (NF-κB), hepatocellular carcinoma (HCC, p70S6K, β-catenin) and acute myeloid leukemia (AML, AP-1)." (PMID 25588053, 2015). "The reference genes of nine hepatocellular carcinoma (HCC) cell lines were systematically evaluated, revealing that TFG and SFRS4 were the most reliable reference genes." (PMID 34458368, 2021). "In contrast to CCA, most of hepatocellular carcinoma tissues (26/29, 89.6%) were negative for TFG staining." (PMID 31754244, 2019).
inflammatory myofibroblastic tumor (3 papers, 2013 to 2025). A multinodular intermediate fibroblastic neoplasm that arises from soft tissue or viscera, in children and young adults. "Additionally, the detection of a TFG::ROS1 fusion in an ALK-negative inflammatory myofibroblastic tumor and the neoadjuvant use of crizotinib in that patient demonstrate the expanding relevance of targeted therapies in pediatric pulmonary malignancies." (PMID 40868080, 2025). "The discovery of ROS1 fusion rearrangements—most notably the TFG::ROS1 oncoprotein—has transformed our understanding of inflammatory myofibroblastic tumor (IMT) biology." (PMID 40868080, 2025). "Many translocations have been found with this ALK gene, including EML4:ALK which is responsible for approximately 3-5% of non-small-cell lung cancer(NSCLC), RANBP2:ALK, TPM4:ALK in inflammatory myofibroblastic tumor, NPM1:ALK, ATIC:ALK, TFG:ALK in anaplastic large cell lymphoma, and so on." (PMID 24564548, 2013).
neuropathy (3 papers, 2015 to 2024). A disorder affecting the nervous system that manifests with pain, tingling, numbness, and/or muscle weakness. "When compared to wild‐type TFG expression, the introduction of neuropathy‐associated TFG variants (i.e., Gly269Val and Pro285Leu) led to a substantial reduction in neurite outgrowth." (PMID 38837630, 2024). "TFG is a TRK-fused gene coded protein, which is a conserved regulator of protein secretion and oncogenesis and has been implicated in neuropathies." (PMID 29180379, 2017). "Interestingly, the TFG mutations affect different domains of the protein: the coil–coil domain in the HSP family, the P/Q rich domain in the family with neuropathy, suggesting different pathological mechanisms." (PMID 25758904, 2015).
chondrosarcoma (2 papers, 2019 to 2020). A malignant cartilaginous matrix-producing mesenchymal neoplasm arising from the bone and soft tissue. "The same holds true for rearrangements involving NR4A3 in extraskeletal myxoid chondrosarcomas: while the AMP-FPS assay covers the most NR4A3 common partners (EWSR1, TAF15, TCF12, TFG) it lacks probes for both NR4A3 and uncommon partners, thus scoring negative in the presence of alternative fusions." (PMID 32351889, 2020).
diabetes (2 papers, 2017 to 2024). "The high coincidence ratio between HMSN-P and diabetes mellitus suggests TFG to have an important role(s) in glucose homeostasis." (PMID 29026155, 2017). "Thus, our results clearly show TFG in β-cell to control insulin secretion in vivo by multiple mechanisms, which could at least partially explain the high coincidence of diabetes mellitus and HMSN-P." (PMID 29026155, 2017).
Insulin resistance (2 papers, 2017 to 2024). Increased resistance towards insulin, that is, diminished effectiveness of insulin in reducing blood glucose levels. "Further studies are needed to clarify the precise molecular mechanisms by which the TFG regulates thyroid hormone actions and PPARγ activities, specifically in vivo, and its therapeutic potential for preventing steatosis and the associated insulin resistance." (PMID 38681675, 2024).
metastatic melanoma (2 papers, 2014 to 2019). A melanoma that has spread from its primary site to another anatomic site. "In addition TFG has been identified as a putative metastatic melanoma tumour suppressor gene and is also thought to play a role in non-small cell lung cancer, acting as a translocation partner for anaplastic lymphoma kinase (ALK)." (PMID 24999993, 2014).
sarcoma (2 papers, 2021). A usually aggressive malignant neoplasm of the soft tissue or bone. "TFG (Trafficking for Endoplasmic Reticulum to Golgi Regulator) has been reported as a 5′ partner in several fusions genes in acute leukemias, sarcomas and carcinomas." (PMID 34745213, 2021). "Although MET fusions are uncommon drivers of sarcoma, a TFG-MET fusion has been reported in a patient with an infantile spindle cell sarcoma with neural features." (PMID 34863095, 2021).
viral infection (2 papers, 2014 to 2021). "Upon virus infection, siRNA-mediated silencing of TFG in HeLa cells markedly decreased production and secretion of IFN-β." (PMID 33411856, 2021). "To this end, we examined the ability of TRAF3 to interact with both MAVS and TBK1 upon viral infection in HEK293T cells in which endogenous TFG was knocked down with a TFG-specific short interfering RNA (siRNA, siTFG)." (PMID 33411856, 2021). "We next tested whether TFG could be involved in the organization of MAVS signalosome networks upon viral infection." (PMID 33411856, 2021). "Thus, TFG expression in cells is important for the production of antiviral proteins following viral infection with an RNA virus." (PMID 33411856, 2021). "Additionally, the TRAF3 substrate TBK1 was also recruited to TFG upon viral infection or stimulation with Poly(I:C)." (PMID 33411856, 2021). "Interestingly, a recent study has suggested that TFG binds TRIM25 upon viral infection and negatively regulates RIG-I-mediated type I IFN signalling." (PMID 24999993, 2014). "Moreover, consistent with previous reports showing the recruitment of TRAF3 to MAVS as an important process leading to downstream signaling, the silencing of TFG also blunted the activating transautophosphorylation of TBK1 on Ser172 (p-TBK1 Ser172) normally observed upon viral infection." (PMID 33411856, 2021). "Here, we present the crosstalk of mTOR and RLR-signaling pathways by demonstrating the requirement of TFG for the interaction of TRAF3 and TBK1 with mTOR upon viral infection." (PMID 33411856, 2021). "Our results detail the functional role of TFG in innate immunity as an ER-to-Golgi resident protein which allows TRAF3 to interact with upstream adapter protein MAVS and downstream kinase TBK1 resulting in activation of TBK1 upon viral infection." (PMID 33411856, 2021). "Therefore, we also performed co-immunoprecipitation of the endogenous proteins to further characterize the dynamics of interaction between TFG and TRAF3 upon viral infection." (PMID 33411856, 2021). "We identify TFG as being part of a molecular complex comprised of at least MAVS, TRAF3 and TBK1 and requirement of TFG in the interactions of TRAF3 with TBK1 and MAVS upon viral infection." (PMID 33411856, 2021).
acute coronary syndrome (1 paper, 2022). Signs and symptoms related to acute ischemia of the myocardium secondary to coronary artery disease. "Next, we analyzed the expression pattern of TFG and pyroptosis-associated genes caspase-1 and NLRP3 using GEO datasets (GSE10220), including 48 macrophage and 48 monocyte samples from 86 patients with symptoms of the acute coronary syndrome." (PMID 35091545, 2022).
amyloidoses (1 paper, 2022). "We therefore conclude that TFG is a novel amyloid protein and propose that the diseases associated with its mutant forms may be amyloidoses." (PMID 35405097, 2022).
amyotrophic lateral sclerosis (1 paper, 2022). Amyotrophic lateral sclerosis (ALS) is a neurodegenerative disease characterized by progressive muscular paralysis reflecting degeneration of motor neurons in the primary motor cortex, corticospinal tracts, brainstem and spinal cord. "And with the identification of new TFG variant, it leads to further understanding of spectrum of TFG and its pathophysiology in amyotrophic lateral sclerosis." (PMID 36582889, 2022).
anemia (1 paper, 2025). A reduction in the number of red blood cells, the amount of hemoglobin, and/or the volume of packed red blood cells. "The first case of TFG::RARA variant APL involved a 16-year-old male who presented with leukopenia, moderate anemia, normal platelet count, and normal fibrinogen levels." (PMID 40386562, 2025).
autoimmune disease (1 paper, 2021). A disorder resulting from loss of function or tissue destruction of an organ or multiple organs, arising from humoral or cellular immune responses of the individual to their own tissue constituents. "Future characterization of TFG’s implication in other PRRs-regulated pathways will undoubtedly help to appreciate the importance of the trafficking secretory pathway in innate immunity and autoimmune diseases." (PMID 33411856, 2021).
clear cell renal carcinoma (1 paper, 2014). A malignant epithelial neoplasm of the kidney characterized by the presence of lipid-containing clear cells within a vascular network. "The chimeras TRIP12->SLC16A14 and TFG->GPR128 have been found in cancer patients with clear cell renal carcinoma." (PMID 25133550, 2014).